APOE (apolipoprotein E)
Diseases named in the same sentence as APOE in open-access papers (continued):
Sharing a sentence is not in itself a finding about the gene and the disease.
cognitive decline (continued). "In this regard, a further limitation is that we did not screen our PD-MCI for APOE genotype which is now considered the main risk factor for cognitive decline in elderly patients with PD and Dementia with Lewy Bodies." (PMID 35300351, 2021). "In EOAD, multivariable analyses showed that APOE ε4 carriers demonstrated slower cognitive decline in general cognitive function (MMSE and CDR-SB, P = .011 and .010), language (P = .010), memory (P = .027), and frontal-executive function (P = .002) than did APOE ε4 non-carriers." (PMID 34127075, 2021). "In the CSF, however, Cp levels were reported not to be elevated in AD but were associated with CSF ApoE levels, longitudinal cognitive decline, and brain volume loss." (PMID 33219130, 2021). "We aimed to determine whether engagement in leisure activities protects against APOE ε4-related cognitive decline." (PMID 34616288, 2021). "Studies also showed that the combination of metabolic rates in the IPL and genetic risks (APOE ε4 carriers) could predict the cognitive decline for preclinical AD detection." (PMID 33994988, 2021). "When combined with sex and APOE genotype, TOMM40 ‘523’ may be a viable prognostic marker, and may assist in understanding the pathology underlying cognitive decline in PD." (PMID 34234128, 2021). "APOE ε4 carrier status was significantly associated with cognitive decline in ASPREE, but PRS was not." (PMID 34041846, 2021). "Although the rate of cognitive decline and the risk of AD are not identical, the presence of complex gene-gene interactions of the APOE gene in both situations should be considered." (PMID 34214049, 2021). "Across all sex and APOE ε4 combinations, women APOE ε4 carriers had the fastest cognitive decline." (PMID 33603015, 2021). "The T allele in SORL1 rs3737529 seems to be protective against cognitive decline independent of APOE genotype." (PMID 34214049, 2021). "A previous VLS study reported a similar pattern, whereby APOE moderation for lifestyle activities (integrative and novel information processing activities) was associated with cognitive decline only in APOE ε4 non-carriers." (PMID 34603005, 2021). "The association between leisure activities and cognitive decline was more pronounced in the group that possessed APOE ε4 alleles in contrast to APOE ε4 allele noncarriers." (PMID 34616288, 2021). "Some studies showed that APOE ε4 was associated with more rapid cognitive decline while others showed APOE ε4 non-carriers have more rapid cognitive decline." (PMID 34127075, 2021). "The current study is carried out in healthy subjects and MCI, which may reveal the role of APOE ε2 in cognitive decline." (PMID 33994988, 2021). "The cumulative incidence of cognitive decline to age 85 years was estimated to be 37.2% (CI 36.4–41.0) in APOE ε3/ε3 homozygotes, 35.3% (CI 30.5–39.6) in ε2/ε2 homozygotes, 45.7% (CI 46.5–53.9) in ε3/ε4 heterozygotes and 52.9% (CI 46.1–76.2) in ε4/ε4 homozygotes." (PMID 34041846, 2021). "As expected, many of the meQTL SNPs within the APOE locus have previously been associated with AD and related traits, such as “cerebrospinal fluid p-tau levels”, “cerebral amyloid deposition (PET imaging)” and “cognitive decline”." (PMID 33397400, 2021). "For example, a recent study showed that non-demented older adults with high PGRS are associated with cognitive decline but this association was no longer present when APOE genotype was removed." (PMID 34603005, 2021). "We did not detect the significant association between carrying APOE ε2 allele and slower cognitive decline, partly due to the small toward nonneuroprotective effect of APOE ε2 at an advanced age." (PMID 34616288, 2021). "Within 6q22.31, TRDN variants have implicated in cerebral Aβ deposition in APOE ε4 non-carriers and rate of cognitive decline in AD." (PMID 34217363, 2021).
cognitive decline (continued). "When we analysed differences in the rate of cognitive decline based on a combination of sex and APOE ε4 status after correcting for LEs, the progression order and significant differences among groups did not change compared to the analysis of data uncorrected for LE." (PMID 33603015, 2021). "We did not observe a significant association between APOE ε2 allele carriers (ε2/ε2, ε2/ε3) and slower cognitive decline compared with the ε3/ε3 reference (data not shown)." (PMID 34616288, 2021). "In our APOE ε4 group, increased circulating DHA was associated with decreased navigation performance, supporting evidence that APOE ε4 disrupts blood−brain barrier function predicting cognitive decline." (PMID 34007965, 2021). "Similarly, individuals carrying high AD-risky apolipoprotein Eε4 (ApoE-ε4) allele showed a BBB breakdown and decreased CBF over time in the frontal, parietal and temporal cortices, preceding the occurrence of cognitive decline." (PMID 34479211, 2021). "Therefore, the protective effect of leisure activities, especially productive activities on cognitive decline, would be more pronounced in APOE ε4 carriers." (PMID 34616288, 2021). "APOE ε4, in addition to older age at onset, depressive mood, and higher H&Y stage, was associated with the cognitive decline rate, but no APOE genotype was associated with motor progression." (PMID 33837234, 2021). "To investigate whether sex and APOE ε4 influence rates of cognitive decline across the AD continuum, we also constructed the disease models by sex and APOE ε4." (PMID 33603015, 2021). "Cognitive decline-death intervals and allelic APOE frequencies in TBI+ vs. TBI– subjects." (PMID 34054681, 2021). "Are patterns of cortical ageing related to APOE e4 status and cognitive decline?" (PMID 33398085, 2021). "There is little research on whether the ApoE gene affects caudate FC in a way that contributes to cognitive decline in PD-MCI." (PMID 33041748, 2020). "Previous studies of the effect of APOE on cognitive decline often used linear regression with the normality assumption, which may not be appropriate for analyzing bounded and skewed neuropsychological test scores." (PMID 33488674, 2020). "The aim of this study is to identify the spatial patterns of tau deposition in cognitively normal older adults and assess whether they are related to amyloid-β (Aβ), APOE, sex, and longitudinal cognitive decline." (PMID 31915896, 2020). "However, for many other tested traits such as clinical disease progression, CSF amyloid, cognitive decline and cortical amyloid load, the additional effects of polygenic scores beyond APOE were of minor nature." (PMID 32226939, 2020). "This will enable us to quantify, with considerable statistical power whether the effect of APOE e4 genotype on brain phenotypes of relevance to cognitive decline and AD is stronger in older age." (PMID 30903549, 2020). "APOE e4 status, however, was a significant predictor of general cognitive decline—those with one or two APOE e4 alleles had significantly steeper general cognitive decline than those who had none—and this association survived multiple-testing correction." (PMID 30760887, 2020). "Like medial temporal atrophy, apolipoprotein E (APOE) ε4 allele genotype, and β-amyloid burden, WML burden is a potentially useful surrogate biomarker with which to monitor cognitive performance and assess cognitive decline." (PMID 32191226, 2020). "In this study, we examine whether there is a gene–environment interaction between APOE and PA on cognitive decline in older adults using 9-year follow-up data of three cohort studies." (PMID 32110803, 2020). "However, for many other tested traits such as clinical disease progression, CSF amyloid, cognitive decline and cortical amyloid load, the additional effects of polygenic burden beyond APOE were of minor nature." (PMID 32226939, 2020).
cognitive decline (continued). "For both ADAS-cog and CDR-SB endpoints, there was a nominal but nonsignificant (α = 6.41 × 10−4) association between APOE genotype (number of ε4 alleles) and cognitive decline (p = 0.019 and p = 0.033, respectively)." (PMID 32370229, 2020). "Similarly, an interaction was also observed between passive jobs and APOE ɛ4 among the younger-old participants in our previous work focusing on cognitive decline." (PMID 32081835, 2020). "To conclude, the present findings replicate and extend previous work by showing that both odor identification performance at baseline, and the interaction of odor identification performance and ApoE-ε4, can be used to predict the magnitude of future cognitive decline." (PMID 31760549, 2020). "However, further evidence for the supplementation of T3 in APOE ε4 carriers with SCD to prevent cognitive decline can only be gathered from a well-designed, randomized clinical trial." (PMID 32671080, 2020). "We found that overall, lower odor identification performance was predictive of cognitive decline, and, as hypothesized, we found that the effect was most pronounced among ApoE-ε4 carriers." (PMID 31760549, 2020). "Here, we aimed to explore whether PA might moderate the effect of APOE genotype on cognitive decline." (PMID 32110803, 2020). "In this study, we sought to address these issues by identifying the spatial patterns of tau in older adults and assessing whether tau in these patterns is related to amyloid, APOE, sex, or longitudinal cognitive decline." (PMID 31915896, 2020). "Recent studies have revealed that ApoE is associated with cognitive decline but not the development of PD." (PMID 33041748, 2020). "Although not much research on the supplementation of thyroid hormones in patients with SCD has been reported to date, we speculate that supplementing T3 in APOE ε4 carriers with SCD might help prevent cognitive decline." (PMID 32671080, 2020). "In this large study conducted among older adults in three prospective population-based cohort studies, we aimed to explore whether PA might moderate the effect of APOE genotype on cognitive decline." (PMID 32110803, 2020). "We hypothesized that baseline olfactory performance would predict cognitive decline within a follow-up interval of six years (2001–2007) and that the effect would be primarily observed in ApoE-ε4 carriers." (PMID 31760549, 2020). "Carriers of the rare allele had poorer average cognitive performance in individuals with at least one APOE ɛ4 allele, and faster cognitive decline in individuals with no APOE ɛ4 alleles." (PMID 30792413, 2019). "Moreover, females with APOE ɛ4 and higher levels of beta-amyloid burden experienced faster rates of cognitive decline than their male counterparts." (PMID 31221191, 2019). "The current study focuses on the ability of cortical morphology in SCD individuals to interact with APOE genotype and anxiety thereby predicting cognitive decline, and hopes to improve the understanding of heterogeneity in SCD and enrich clinical trials on SCD." (PMID 31159873, 2019). "The cognitive decline seen in individuals with increased WMH burden and the cognitive decline found in persons with the ApoE promoter genotypes tested here do not seem to be associated." (PMID 31551090, 2019). "Homozygous subjects had the most rapid memory decline, indicating that the APOE ε4 effect on cognitive decline may be dependent on gene dose." (PMID 30866553, 2019). "This suggests that the associations of olfactory impairment with accelerated cognitive decline and volumetric differences were independent of APOE ε4." (PMID 30651382, 2019). "Because inducible expression of APOE to facilitate Aβ clearance, reorganize synaptic disruption, and slow cognitive decline may provide novel approaches to AD treatment, there is a critical need to dissect the effects of APOE on AD biomarkers." (PMID 31831047, 2019).
cognitive decline (continued). "In addition to cognitive status, APOE ε4 is also related to accelerated cognitive decline in old adults, particularly in memory." (PMID 30866553, 2019). "Likewise, an augmentation of CSF ApoE levels was also related to higher CSF tau levels and cognitive decline in human." (PMID 30935111, 2019). "It has an additional 6 cohorts (including from 3 new countries) relative to our earlier study of cognitive decline in COSMIC cohorts, but more importantly includes a wide range of risk factors, beyond only those of age, sex, education, and APOE*4 carriage that we previously investigated." (PMID 31335910, 2019). "We investigated the impact rs17070145 has on the rate of cognitive decline and hippocampal atrophy over six years in 602 CN adults, with known brain Aβ-amyloid levels and whether there is an interactive effect with APOE genotype." (PMID 29391469, 2018). "This indicates a faster rate of cognitive decline for those individuals homozygous for APOE-ε4." (PMID 29317609, 2018). "Having at least one risky APOE allele was associated with more rapid longitudinal cognitive decline compared to those with no risky alleles." (PMID 30339707, 2018). "Oxidative damage in hippocampus is consistent with our previous demonstration of cognitive decline following maintenance of ApoE-/- mice on a diet that fostered oxidative damage to overall brain tissue, and alleviation of cognitive decline by supplementation with antioxidants." (PMID 29541261, 2018). "In the present study, we tested whether the effects of depressive symptoms, neuroticism and AL on baseline general cognitive ability and subsequent general cognitive decline were moderated by APOE E4 possession." (PMID 29451880, 2018). "Genetically in LOAD, the apolipoprotein E(APOE) gene is the strong factor to cognitive decline." (PMID 30563553, 2018). "The ε4 allele of APOE has been found to be associated with longitudinal cognitive decline in non-demented study participants." (PMID 30339707, 2018). "Possession of the E4 allele of the APOE gene has been linked to higher risk of late-onset Alzheimer’s disease as well as lower cognitive ability and greater cognitive decline in non-clinical groups of older adults." (PMID 29451880, 2018). "We examined whether variations in apolipoprotein E (ApoE) and microtubule-associated protein tau (MAPT) genotypes are associated with cognitive decline in PD." (PMID 30155299, 2018). "As for white European-ancestry populations, results on APOE and non-pathogenic cognitive decline in Asian populations have been mixed." (PMID 30339707, 2018). "Accounting for the underlying Aβ-amyloid burden in the current study may have further contributed to the detection of differences in rates of cognitive decline and hippocampal atrophy reported with APOE ε4 and KIBRA." (PMID 29391469, 2018). "The presence of an APOE ε4 allele, smoking, lower physical fitness and lower vitamin B-12 were all associated with greater relative nonpathological lifetime cognitive decline." (PMID 29745686, 2018). "Although APOE is well-established regarding its major role in cognitive decline in elder adults, the biologically synergistic effects between the APOE and REST genes on cognitive aging are still unknown." (PMID 29209239, 2017). "However, APN has previously been associated with prospective cognitive decline in Mild Cognitive Impairment (MCI), and that effect was fully attenuated by APOE adjustment, suggesting an association." (PMID 28291794, 2017). "However, CSF t-tau levels had a strong influence on the relationship between cortical plasticity and cognitive decline depending on the APOE genotype." (PMID 29062035, 2017). "If APOE ɛ4 genotype results in increasing cognitive deficits over the life span, then middle-aged individuals might be expected to show cognitive decline on sensitive tasks." (PMID 27395443, 2016).
cognitive decline (continued). "We have proved that cognitive decline of ApoE-KO mice might be obviously ameliorated with long-term administration of 7,8-DHF." (PMID 27965573, 2016). "Significantly, use of CCBs ameliorated the negative effects of the presence of APOE-4 alleles on cognitive decline." (PMID 26221415, 2015). "The aim of this study was to investigate the relationship between cerebral Aβ level, APOE ε4 carrier status, and cognitive decline over 18 months, in 317 cognitively healthy (CN) older adults (47.6% males, 52.4% females) aged between 60 and 89 years (Mean = 69.9, SD = 6.8)." (PMID 26430784, 2015). "The level of cognitive decline among those with a high genetic risk score in the absence of APOE ε4 was not statistically significantly different than the level of decline in individuals with a low genetic risk score." (PMID 26102276, 2015). "Among those with one or more APOE ε4 alleles, having one or more copies of the CD33 C (risk) allele may further increase the risk of cognitive decline." (PMID 26102276, 2015). "Numerous studies have evidenced that β-amyloid burden might occur many years before objective or subjective cognitive declines, especially among APOE-ε4 carriers." (PMID 26053677, 2015). "However, further studies in humans and Tg-mouse models are critical to determine the role of potential interactive effects among Aβ pathology, APOE genotype and sex on memory and cognitive decline." (PMID 25871877, 2015). "Several previous studies have suggested that the APOE ε4 allele is associated with a faster rate of cognitive decline, rather than cognitive impairment, at the first visit." (PMID 24914687, 2014). "A lower level of plasma ApoE may impair the normal physiological functions of ApoE, contributing to cognitive decline and degeneration of CNS." (PMID 24558469, 2014). "MCI carriers of the APOE e4 allele manifested more atrophy and presented a faster cognitive decline when compared to non-carriers." (PMID 25071554, 2014). "The precise neurophysiological mechanisms by which PA might protect human APOE-ε4 carriers from cognitive decline and AD-related neuropathology are less well understood." (PMID 24795624, 2014). "In Korean adults, UACR values were independently and negatively associated with cognitive performance, and APOE E4 carriers showed a steeper cognitive decline compared to E4 noncarriers." (PMID 25530658, 2014). "Additionally, our analysis included adjustments for several potential covariates, such as the status of APOE, that affect not only pathogenesis (e.g., Aβ aggregation or neural toxicity) but cognitive decline." (PMID 24694100, 2014). "Non-modifiable factors associated with both cognitive decline and dementia include age, sex and genetics (particularly APOE genes)." (PMID 24885250, 2014). "Some studies report a positive relationship of APOE ε4 with more rapid cognitive decline in mild and mild-to-moderate AD, while others report no significant influence on the rate of cognitive and functional progression, or that individuals with two ε4 alleles have a slower clinical course of AD." (PMID 24099236, 2013). "Adjustment for possible risk factors for cognitive decline, such as diabetes mellitus, cardiovascular diseases, alcohol use, smoking, systemic inflammation and APOE genotype did not change the results." (PMID 23483953, 2013). "In the current study, the presence of at least one APOE ε4 allele was associated with a faster rate of cognitive decline when using the ADAS-cog scale but not the MMSE." (PMID 24099236, 2013). "The central question we try to answer is whether increasing or decreasing apoE level and/or function will serve best to reduce AD/DS pathology and cognitive decline." (PMID 22844635, 2012). "Given that the sample may be at a critical age for the onset of decline, we hypothesized that the rate of cognitive decline over the four years from Wave 1 to Wave 2 would be greater for APOE *E4 carriers." (PMID 18620605, 2008).